CCND1 (cyclin D1)
Diseases named in the same sentence as CCND1 in open-access papers (continued):
Sharing a sentence is not in itself a finding about the gene and the disease.
esophageal cancer (continued). "Although overexpression of miR-199a-5p and downregulation of MAP3K11 may affect proliferation through other mechanisms not evaluated in this study, these data support an important role for cyclin D1 in mediating the observed decreased proliferation in esophageal cancer cells." (PMID 26717044, 2016). "Pyrotinib treatment reduced the cyclin D1 and cyclin-dependent kinase 4 (CDK4) levels for increasing G0/G1 arrest, resulting in the enhanced anti-proliferation effects of radiotherapy in esophageal cancer cells." (PMID 39193330, 2024). "In esophageal cancers, CDKN2A, CDKN2B, and CCND1 alterations in the cell cycle pathway were frequently observed." (PMID 38672586, 2024). "In esophageal cancer, dysregulation of the FBXO4-cyclin D1-RB axis promotes glutamine addiction and highlights a therapeutic weakness for overcoming CDK4/6 inhibitor resistance." (PMID 35877430, 2022). "Results indicated that the expression of four target genes (CCND1, CASP3, EGFR, and CDC42) was markedly upregulated in esophageal carcinoma." (PMID 32412911, 2020). "Expression analysis of miR-196a-5p and miR-1-3p targets in TCGA using the UALCAN tool showed that CCND1, CASP3, EGFR, and CDC42 were overexpressed in esophageal carcinoma, compared to normal esophagus samples." (PMID 32412911, 2020). "For example, most of the genes on the trunk of sample ESCC12 (CCND1, EGFR, APC, TGFBR2, XPC, XPA, FLI1, and NUMA1) have been identified and initially reported on the esophageal cancer." (PMID 30540749, 2018). "In addition, the expression of cyclin D1, MYC, MMP2, and molecules involved in the NF‐κB signaling pathway was increased in esophageal cancer cells, similarly as observed for PD‐L1." (PMID 40790948, 2025). "However, the top ranking list of oncogene focal amplifications was different between esophageal cancer and GCAs, where CCND1 and EGFR were the top two ranking oncogene focal amplifications in the esophageal cancer." (PMID 34764264, 2021). "Consistently, we found that pyrotinib could reduce cyclin D1 and CDK4 levels in esophageal cancer cells." (PMID 32022229, 2020). "Given the critical role of NFκB in cell growth and survival, it is conceivable that, in addition to cyclin D1 and c-Myc, NFκB may mediate the effects of STAT3 on esophageal cancers." (PMID 29179470, 2017). "Furthermore, it has been demonstrated that the overexpression of cyclin D1, rather than cyclin E, is involved in the pathogenesis of esophageal cancer." (PMID 24348764, 2014). "Although a loss of antisense-transfected cells during clonal expansion has been described, for example, in oesophageal cancer cells with antisense to cyclin D1, no such phenomenon has ever been reported using antisense oligomers or antisense expression vectors against the K-ras gene." (PMID 12373606, 2002).
leukemia (78 papers, 2007 to 2026). A malignant (clonal) hematologic disorder, involving hematopoietic stem cells and characterized by the presence of primitive or atypical myeloid or lymphoid cells in the bone marrow and the blood. "Among the genes with significant changes upon TMIGD2 depletion were factors closely associated with cell-cycle (CDKN1A and CCND1) and leukemia stemness (CD93 and IL1RAP)." (PMID 38167704, 2024). "In leukemia, JAM3 maintains leukemia-initiating cell function through the LRP5/AKT/β-catenin/CCND1 signaling pathway and is associated with poor prognosis in leukemia." (PMID 38400838, 2024). "Point mutations of LEF1 located in exons 2 (K86E) and 3 (P106L) of LEF1 result in increased promoter activity and expression for c-myc and cyclin D1, causing increased leukemia cell proliferation." (PMID 38003292, 2023). "It has been reported that CCND1 G870A polymorphism is associated with the risk of leukemia and toxicity of MTX in ALL." (PMID 31874600, 2019). "In addition, we observed downregulation of leukemia-associated proto-oncogenes such as CCND1/2 (0.46, p < 0.05), CCNE2 (0.38 p = 0.0076), MYC (0.42, p < 0.001), SRC (0.3, p < 10−5), or MPL (0.25, p < 0.05)." (PMID 41438051, 2025). "B1 showed nanomolar cytotoxicity (IC50 = 0.04 μM) against MV4-11 leukemia cells by inducing G0/G1 arrest (via cyclin D1/CDK6 downregulation) and apoptosis." (PMID 41745466, 2026). "In parallel, CCND1 has been shown to be negatively regulated by miR-342-5p in leukemia cells and in vivo models, highlighting the role of this miRNA in controlling pathways related to cellular differentiation and proliferation." (PMID 41596334, 2026). "Our present study proved that the expression levels of CDK2, CDK4, Cyclin D1 and Cyclin E were more abundant in the chemo-resistant leukemia cells than in their parental cells." (PMID 37814227, 2023). "The proliferation of leukemia cells and inducing apoptosis has been inhibited by Circ_PTK2 silencing with reducing cyclin D1 expression and Bcl-2/Bax level regulation." (PMID 37124518, 2023). "Mambalgin-2 was shown to suppress theactivity of these channels and to inhibit leukemia cell proliferation bycausing G1-phase cell cycle arrest and reducing the activity of the cell cycleregulators cyclin D1 and cyclin- dependent kinase CDK4." (PMID 32742733, 2020). "Previous reports demonstrated the inhibitory roles of JARID2 in leukemia cell differentiation via regulating cyclin D1." (PMID 31700696, 2019). "STAT5 induces the expression of its target genes, such as, cyclin D1, c-myc and the protooncogene Pim-1, which mediates the proliferative and antiapoptotic behavior of leukemia cells via the FLT3-ITD signaling pathway." (PMID 31434952, 2019). "Gallic acid, which is a structurally similar phenolic acid, induced G1 phase arrest in human leukemia HL-60 cells through inhibiting cyclin D1 pathway, which fortifies our results." (PMID 29518944, 2018). "Targeting mTORC2 has been found to suppress Cyclin D1 translation via inhibiting recruitment of Cyclin D1 mRNA to polysome in leukemia cells." (PMID 27031247, 2016). "For example, cyclin D1 levels are increased in high-risk MDS, thereby increasing the proliferation of leukemia." (PMID 24926340, 2014). "RNF220 stimulates the growth of leukemia cells by diminishing the breakdown of Cyclin D1 protein." (PMID 39048945, 2024). "Our above results suggest that higher expression levels of Cyclin D1 and Cyclin E were closely related to chemotherapy tolerance and might be one of the reasons for drastic drug resistance in leukemia cells." (PMID 37814227, 2023). "We found the novel LEF1 mutations could promote the cell proliferation of leukemia cells by regulation of gene expression of LEF1 targets: c-MYC and Cyclin D1." (PMID 25942645, 2015). "The elevated cyclin D1 in our study may indicate deregulation of cell cycle and apoptosis in HS/PCs, which may be responsible for the pathogenesis of benzene-induced leukemia." (PMID 26262635, 2015).
leukemia (continued). "Besides, the CCND1 (cyclin D1) is the target of the drug arsenic trioxide, which is used to treat leukemia." (PMID 25818893, 2015). "There are few studies on the effects of cyclin D1 on leukemia either domestically or abroad." (PMID 22848779, 2012). "Some of these genes, such as Ccnd1 and Myc, are largely known to be involved in leukaemia." (PMID 20102610, 2010). "In order to examine whether this comparative overexpression of transcripts was correlated with protein levels, we assessed by western blotting the expression of CDK4, cyclin D1 and Rb in Ewing sarcoma cells, mesenchymal stem cells, leukemia cell lines and neuroblastoma cells." (PMID 26337082, 2015). "Validated targets concentrated on key leukemia-related genes like PTEN, BCL2L11, CDKN1A, CCND1, RB1, E2F1, and TGFBR2." (PMID 42123456, 2026). "Leukemia patients with overexpression of ITGA2, COL6A1, cyclin D1, PKN1, PDGFRA, or F2R predict or have trends toward worse prognosis." (PMID 41203598, 2025). "At the cellular level, SFX-01 induced STAT1 phosphorylation, suppressed cyclin D1 expression and promoted PKR activation, collectively leading to growth arrest in leukocytes and Shp2-mutant leukemia cell lines." (PMID 40640547, 2025). "Leukemia patients with overexpression of ITGA2, COL6A1, cyclin D1, PKN1, PDGFRA or F2R predicts or has trends toward worse prognosis." (PMID 39764125, 2024). "The results indicated that KYN significantly increased cell proliferation marker expression (cyclin D1, E2F1, and Ki-67), as well as IDO1, TDO2, Ikaros1, AML1, and ETV6 expression, in leukemia cells." (PMID 35687267, 2023). "Compared with parental sensitive leukemia cells, the protein expression levels of CDK2, CDK4, Cyclin D1 and Cyclin E in chemo-resistant leukemia cells were relatively elevated." (PMID 37814227, 2023). "Comparing with their parental sensitive leukemia cells, the protein expression levels of CDK2, CDK4, Cyclin E and Cyclin D1 relatively elevated in chemo-resistant leukemia cells." (PMID 37814227, 2023). "JAM3 is highly enriched in leukemia-initiating cells and play an important role in the maintenance of leukemia-initiating cell stemness through LRP5/PDK1/AKT/GSK3β/β-catenin/CCND1 signaling pathways." (PMID 32979257, 2020). "Most importantly, alpelisib therapy in NSGS mice bearing nilotinib-resistant K562 cells significantly reduces leukemia burden and increases the survival time of leukemic mice, mechanistically through suppression of PI3K signaling mediators like F2R, Cyclin D1, and PDGFR." (PMID 41203598, 2025). "Consistent with this, exposure to MWCNT bucky paper was shown previously to reduce the expression of CCND1/CDK4 as well as cell proliferation by triggering cell cycle arrest in G0/G1 phase and increase apoptosis in human leukemia cell lines through modulation of AKT and MAPK signaling pathways." (PMID 26930275, 2016). "The immunohistochemical study revealed that 90% of the CD20+ lymphoid cells were CD25+; Cyclin D1+ cells were positive in a small percentage of the leukemia cells; CD1a, TdT, and CD10 were not expressed by the bone marrow cells; and CD34+ cells were present in 1–2% of the blasts." (PMID 40126222, 2025). "Further immunostaining was negative for cyclin-D1 and SOX11 and positive for CD43 and LEF1, overall consistent with CLL/SLL-induced subcutaneous leukemia cutis." (PMID 40893576, 2025). "It is important to note that both CCND1 and BCL2L1 gene expression also were decreased significantly in leukemia cell lines NB4 and HL-60, which do not have MLL rearrangement." (PMID 24858818, 2014).
oral cancer (78 papers, 1999 to 2025). "The research examined the link between H-Ras (C81T) and cyclin D1 (A870G and C1722G) gene SNPs and oral cancer risk in 176 oral cancer cases and 142 hospital-based controls matched for age and sex." (PMID 38420094, 2024). "The proposed mechanism of therapeutic resistance to EGFR TKIs include constant stimulation of downstream signaling pathways by mutated RAS gene in oral cancer via special group of genes such as CCND1, c-MYC, BCL-XL and BCL-2." (PMID 35047986, 2020). "It has also been proposed that CDKN2A chromosomal abnormalities are frequently linked with cyclin D1 gene overexpression in oral cancer." (PMID 35047986, 2020). "With the induction of COX-2, expression of oral cancer-associated genes cyclin D1 was upregulated and p16 was downregulated." (PMID 31448061, 2019). "The overall estimates indicated that cyclin D1 overexpression was significantly associated with increased risk of nodal metastasis (N1, 2, 3 versus N0) in oral cancer patients (OR = 2.035, 95% CI = 1.572–2.635)." (PMID 24675814, 2014). "Evidence suggests that gene amplification and protein overexpression of CCND1 were detected in a number of cancers, including oral cancer, and were considered to be associated with a poor prognosis." (PMID 23170138, 2012). "Meta-analyses examining the association between CCND1 G870A polymorphisms and oral carcinoma were performed." (PMID 23170138, 2012). "Higher expression of cyclin D1 in oral cancer appears to be closely linked to cell proliferation, differentiation and lymph node invasion." (PMID 21537090, 2011). "Cyclin D1 was associated with tumorigenesis and proliferation of oral cancer." (PMID 36532636, 2022). "In addition, we found that with the induction of COX-2, expression of the oral cancer-associated genes cyclin D1 was upregulated and p16 was downregulated." (PMID 35859766, 2022). "Compared with our meta-analysis of Asian populations, these disparities may exclude racial difference in the association between cyclin D1 expression and oral cancer development." (PMID 24675814, 2014). "As a single study may have been underpowered in clarifying the associations of CCND1 G870A polymorphisms with oral carcinoma susceptibility, in the present study we performed evidence-based quantitative meta-analyses that increased statistical power to address this controversy." (PMID 23170138, 2012). "Thus, evaluation of the association of CCND1 polymorphism with oral cancer risk is required." (PMID 23170138, 2012). "In this sense, Cyclin D1 is a promising target for oral cancer treatment, with ongoing research focusing on developing effective therapeutic strategies to combat OSCC." (PMID 39937256, 2025). "CBN/PVP induced cell-cycle arrest in the G1 phase, concomitantly with a significant downregulation of Cyclin D1, which is known as a positive controller of the cell cycle and is often overexpressed in oral cancer." (PMID 40137387, 2025). "BEZ235, an inhibitor of PI3K/Akt/mTOR signaling and the cyclin D1/CDK-4 complex, was shown to cause synergistic radiosensitization in oral cancer cells." (PMID 40940957, 2025). "Similar to our findings, it has been shown that inhibited proliferation and induced apoptosis of oral carcinoma cells upon administration of metal oxide NPs were mediated by downregulation of CCND1." (PMID 36949885, 2023). "Among these, HIF1α, CDH1, CD44, EGFR, and CCND1 were identified as the top hub genes that have also been reported as driver candidates responsible for oral cancer initiation and progression." (PMID 37316916, 2023). "This mutation is a 133 Kb duplication of three fibroblast growth factor (FGF) genes (FGF3, FGF4, FGF19), the oral cancer overexpressed gene (ORAOV1), and the CCND1 gene, which encodes cyclin D1." (PMID 36006348, 2022). "Cyclin D1 upregulation with amplification of CCND1 has been documented in various malignancies including breast, lung, colon, and oral cancers." (PMID 35484605, 2022).
oral cancer (continued). "Following induction of oral cancer in an animal 4NQO model, it was reported that the expression of CCND1 decreased when the animals were exposed to substances with antitumor activity." (PMID 32104177, 2020). "This feature is also evident in this study where in the control group of rats induced for oral cancer, the cyclin D1 expression by immunohistochemistry was found in the parabasal and basal compartments of the keratinised epithelium." (PMID 32104177, 2020). "The activation of the pathways involved in cyclin D1 expression appears to be essential in the development of human cancers, including oral cancer." (PMID 29785357, 2018). "Through bioinformatics analysis of the gene expression profile of oral cancer metastatic and non-metastatic lymph nodes and primary tumors, we identified a new oral cancer metastatic gene signature: CCND1, JUN and SPP1." (PMID 30459815, 2018). "In this study, we found that melatonin impaired the proliferation and apoptosis resistance of oral cancer cells by inactivating ROS-dependent Akt signaling, involving in downregulation of cyclin D1, PCNA, and Bcl-2 and upregulation of Bax." (PMID 29725496, 2018). "The results suggested the important function of CCND1 in promoting oral cancer lymph node metastasis although the detained mechanism still needs to be explored." (PMID 30459815, 2018). "The rationale of choosing these CNA associated genes was basically due to LRP12, TPM2, EGFR, CCND1 being matched with ICGC and TCGA databases whereas FSCN1, CLPTM1L, CHL1 and CSMD1 had been found to be associated with oral cancer." (PMID 28384287, 2017). "For instance, the progressive inactivation of GSK-3β was observed in oral carcinoma, with a positive correlation between the expression of pS9GSK-3β and cyclin D1." (PMID 26418031, 2015). "Considerable evidence has shown that while cyclin D1 and cyclin E are upregulated 14,33, the CDKIs including p21Cip1 and p 27Kip1 are downregulated in human oral cancers 15,16." (PMID 25644496, 2015). "We used the odds ratio (OR) and hazard ratio (HR) as the common measures of association to quantitatively determine the correlation between cyclin D1 overexpression and outcomes of oral cancer." (PMID 24675814, 2014). "Both cyclin D1 and loss of p21cip1/waf1 have been shown to mediate the antiproliferative activity of PEG in the colon, thereby mirroring the current findings in oral cancer." (PMID 22675506, 2012). "The results are consistent with our previous studies showing that high CCND1 expression correlated with cisplatin resistance in oral cancer cells, in vitro and in vivo." (PMID 22065993, 2011). "Recently, we demonstrated overexpression of PI Synthase, PI3-K and cyclin D1 in ST treated cells from oral lesions and oral cancer." (PMID 21383988, 2011). "We also studied the expression of EGFR, β-catenin, and cyclin D1 in 112 samples of oral cancer by immunostaining." (PMID 20302655, 2010). "For example, it is known that cyclin D1 amplification participates in overexpression of this gene in oral cancer." (PMID 20302655, 2010). "This study, to our knowledge, is the first report demonstrating overexpression of PI Synthase, PI3-K and cyclin D1 in ST treated cells from oral lesions and oral cancer." (PMID 20426864, 2010).